RNU6-272P (RNA, U6 small nuclear 272, pseudogene)
Gene: Small nuclear RNA gene on chromosome 5 (53,912,020 to 53,912,123, reverse strand). Ensembl gene ENSG00000222960.
Homologues: Orthologues: chimpanzee U6 (97% identical), macaque U6 (94% identical). Paralogues in human: RNU6-797P (91% identical), RNU6-1091P (88% identical), RNU6-727P (88% identical), RNU6-1243P (88% identical), RNU6-1287P (88% identical), RNU6-668P (87% identical), RNU6-1047P (86% identical), RNU6-445P (86% identical), RNU6-711P (86% identical), RNU6-879P (86% identical), RNU6-1060P (85% identical), RNU6-1159P (85% identical), and 1288 more.